ERBB2 (erb-b2 receptor tyrosine kinase 2)
Diseases named in the same sentence as ERBB2 in open-access papers (continued):
Sharing a sentence is not in itself a finding about the gene and the disease.
gastric cancer (continued). "This is in accord with a report that most ERBB2-positive gastric cancers have several additional co-existing abnormalities such as focal amplifications and somatic mutations of other oncogenes and cell cycle genes." (PMID 29872697, 2017). "The migration and invasion of gastric cancer cells was inhibited by miR-1296-5p overexpression or herceptin treatment, and rescued by the overexpression of constitutively active Rac1-Q61L or ERBB2." (PMID 28099468, 2017). "Here we investigated the role of possible tumor-suppressor miR-1296-5p in the cell migration and invasion of ERBB2-positive gastric cancer." (PMID 28099468, 2017). "Collectively, these findings cement the fact that miR-1296-5p is a novel regulator of ERBB2 in gastric cancers." (PMID 28099468, 2017). "In the present study, we report an important function of APIP in ERBB2/ERBB3 signaling in gastric cancer." (PMID 26942872, 2016). "ErbB2 inhibitors have recently been approved for the treatment of ErbB2-positive gastric cancers; therefore, we next investigated the feedback control of ErbB2 in MKN45 human gastric cancer cells." (PMID 27531070, 2016). "Subsequently, several RTKs have been identified as drivers of tumor development in gastric cancers including HER2/ERBB2, VEGFR, PDGFR, FGFR, IGFR, and Met." (PMID 27781065, 2016). "Overall, these results suggest that APIP stimulates cell proliferation via ERBB3, acting in conjunction with ERBB2, in gastric cancer cells." (PMID 26942872, 2016). "Testing for the presence of HER2 (ERBB2) gene amplification for the prediction of the tumor response to anticancer treatment by anti-ERBB2 monoclonal antibody has fundamentally transformed the oncology of gastric cancer." (PMID 27781065, 2016). "Recently, DNA aptamers targeting human epidermal growth factor receptor 2 (ErbB-2/HER2) was demonstrated to retard the tumorigenic growth of gastric cancer in mice with more effective activity than anti-ErbB-2/HER2 monoclonal antibody." (PMID 26610462, 2015). "For example, a significant portion of human breast, ovarian, and gastric cancer cells overexpress ErbB2 or have ErbB2 gene amplification." (PMID 24824849, 2014). "HER2 (ERBB2) overexpression varied according to gastric cancer subtypes and targeting HER2 through the use of a humanized monoclonal antibody Trastuzumab (Herceptin) has been very successful in the treatment of HER2-overexpressed gastric cancers." (PMID 25025766, 2014). "ERBB2 expression is also an important predictor of gastric cancer patient classification, which is used for further specific therapies." (PMID 24926380, 2014). "For example, trastuzumab was approved in combination with chemotherapy for the treatment of ERBB2-positive gastric cancers." (PMID 25025766, 2014). "The humanized antibody trastuzumab (Herceptin) against the overexpressed ErbB2 is proven to be effective in treating breast and gastric cancers with ErbB2 amplification." (PMID 25238247, 2014). "In the present study, miR-375 was shown to be downregulated in gastric cancer tissues, particularly human epidermal growth factor receptor 2 (ERBB2)-positive gastric cancer tissues." (PMID 24926380, 2014). "Amplification, overexpression or both, of human epidermal growth factor receptor-2 (HER2, also known as ERBB2), a transmembrane receptor tyrosine kinase, is present in around 6.1–23.0% of gastric cancers." (PMID 25380654, 2014). "Recent data have shown that in gastric tumors, flotillin-2 expression correlates with HER2/ErbB2 levels and flotillin-2 knockdown in a gastric cancer cell line results in reduced HER2 expression." (PMID 24304721, 2013). "ErbB2 protein overexpression in association with ErbB2 gene amplification is an excellent biomarker for anti-ErbB2 therapies in breast and gastric cancers." (PMID 23519149, 2013).
gastric cancer (continued). "Other human tumor types have also been reported to harbor ERBB2 amplification or overexpression, including lung cancers, gastric cancers, ovarian cancers, prostate cancers, salivary gland tumors, and bladder cancers." (PMID 23630663, 2013). "Genomic DNA amplification is a genetic factor involved in cancer, and some oncogenes, such as ERBB2, are highly amplified in gastric cancer." (PMID 22591714, 2012). "Correlation between ERBB2 amplification and overexpression is noted by comparing aCGH and expression array data in our gastric cancer data set." (PMID 22539939, 2012). "Our data indicated that ERBB2 and EGFR genetic abnormalities were associated with the prognosis of gastric cancer." (PMID 21689422, 2011). "IHC was first used in 1986 to detect ERBB2 expression in gastric cancer, which was followed by a large number of similar reports." (PMID 21689422, 2011). "Presently, much of the available knowledge regarding EGFR and ERBB2 expression as well as their biological function in gastric cancer has come from countries other than China." (PMID 21689422, 2011). "For example; in gastric cancers the frequently amplified 17q12-q21 region contains genes such as ERBB2, GRB7, JUP, PERLD1, PNMT, PPP1R1B, STARD3, and TOP2A." (PMID 20187983, 2010). "To clarify the potential clinical relevance of ERBB2 status in gastric cancer, we have characterised its overexpression and amplification in 463 patients with clinicopathological data and a follow-up time of 6–10 years." (PMID 19156142, 2009). "A large-scale clinical study is currently being carried out to compare the response to chemotherapy combined with trastuzumab vs chemotherapy alone in gastric carcinoma patients with ERBB2 amplification." (PMID 19156142, 2009). "In this study, we evaluated the ERBB2 status in 463 gastric carcinomas using immunohistochemistry (IHC) and fluorescence in situ hybridisation (FISH), and compared the findings with histopathological characteristics and with disease-specific survival." (PMID 19156142, 2009). "The first goal of this study was to clarify the frequency of ERBB2 overexpression and amplification in a large series of gastric carcinoma patients (n=463)." (PMID 19156142, 2009). "In two mixed gastric carcinomas containing both isolated cells and glandular components, ERBB2 overexpression and amplification were found in both histological patterns." (PMID 19156142, 2009). "Earlier studies in gastric carcinomas reported ERBB2 overexpression using immunohistochemistry (IHC) in 5.2–22.6% of the cases, whereas the proportion with ERBB2 amplification evaluated using fluorescence in situ hybridisation (FISH) ranged from 3.8 to 12.2%." (PMID 19156142, 2009). "Several authors have earlier stated that ERBB2 amplification is an exclusive event of intestinal-type gastric carcinomas." (PMID 19156142, 2009). "In gastric cancer, a correlation between ErbB2 gene amplification and prognosis of patients has been reported." (PMID 18781152, 2008). "In gastric carcinoma ERBB2 amplification was detected preferentially in intestinal carcinomas of the stomach." (PMID 18199332, 2008). "In gastric carcinoma it has been shown that ERBB2 overexpression is driven by gene amplification and is associated to carcinomas with high invasive potential." (PMID 18199332, 2008). "The NCCN Gastric Cancer Guidelines adopt the same testing approach and recommend testing at the time of diagnosis of metastatic disease or relapse, with consideration of NGS to detect actionable ERBB2 mutations in selected patients." (PMID 41463236, 2025). "This study reports two patients with unresectable, HER2-positive (IHC-confirmed or ERBB2-amplified) advanced gastric cancer who received first-line therapy with the domestically developed anti-HER2 monoclonal antibody inetetamab combined with PD-1 inhibition and XELOX chemotherapy." (PMID 41220939, 2025).
gastric cancer (continued). "In addition, we reported that RUNX1 regulates ErbB2/HER2 signaling pathway in HER2‐positive gastric cancer cells through transactivating SOS1 expression, rendering itself an ideal target for antitumor strategy toward this cancer." (PMID 40171874, 2025). "Therefore, based on its strong binding affinity to ERBB2 demonstrated through molecular docking, ursolic acid is suggested as a novel therapeutic approach for gastric cancer." (PMID 40141751, 2025). "However, later studies demonstrated that gastric cancer cells that exhibit dramatic reductions in the expression of various tyrosine kinase receptors (TKRs), including HER2/ERBB2, are resistant to TKR inhibitors but sensitive to mubritinib." (PMID 39901019, 2025). "Recent developments in regard to antibody–drug conjugates targeting ERBB2, such as trastuzumab deruxtecan (T-DXd), have demonstrated promising efficacy in regard to ERBB2-positive gastric cancer, and their activity in the context of specific ERBB2 mutations warrants further investigation." (PMID 40699829, 2025). "In the context of the present cohort, no targetable mutations in the ERBB2 gene were identified in the five cases of gastric cancer (three of which exhibited metastases)." (PMID 41515496, 2025). "We also observed the 3oc-induced TGF-β/ErbB2 network activation and trastuzumab resistance in gastric cancer cells, suggesting that the results we obtained may be a general phenomenon." (PMID 39786928, 2025). "In gastric cancers, ERBB2 alterations in the RTK pathway were observed." (PMID 38672586, 2024). "R. J. Wang inhibited gastric cancer growth and metastasis in vitro, which may be related to the inhibition of the ERBB2/ERBB3/PI3K/AKT pathway." (PMID 39549017, 2024). "Several amplified genes including ERBB2, FGFR2, MET, TNK2 have been identified significantly associated with advanced tumor grade and heightened aggressiveness in gastric cancer." (PMID 39052108, 2024). "In gastric cancer, ERBB2 alterations are mainly present in the chromosomal unstable (CIN) subtype." (PMID 38611014, 2024). "The most frequently amplified oncogenes in gastric cancers, including MYC, ERBB2 (encoding for HER2), and CCNE1 (encoding for cyclin E), showed higher prevalence in the higher CDX2-expressing group, which was statistically significant for MYC (Fisher’s exact test p = 0.008)." (PMID 39768557, 2024). "HER2 protein overexpression or amplification of the ERBB2 gene serves as a crucial predictive biomarker for identifying breast or gastric cancer patients who may benefit from HER2‐targeted therapies." (PMID 38895905, 2024). "However, our study is the first to demonstrate that miR-497-5p specifically promotes the mRNA degradation of ERBB2, thereby inhibiting the expression of ERBB2 protein and suppressing the malignant behavior of gastric cancer cells." (PMID 38911367, 2024). "In HER2‐positive gastric cancer, ERBB2 copy number predicts the response to trastuzumab plus chemotherapy, but we were unable to assess whether ERBB2 copy number affected the observed responses to T‐DM1." (PMID 37119523, 2023). "In contrast, the currently recommended molecular-targeted therapies for gastric cancer are trastuzumab, which targets erb-b2 receptor tyrosine kinase 2 (ERRB2) (also known as HER2), and ramucirumab, which targets kinase insert domain receptor (KDR) (also known as VEGFR2)." (PMID 35409367, 2022). "We also found that ERBB2d16 expression resists gastric cell death in patients treated with trustuzumab, and the ERBB2d16/ERBB2 ratio may serve as a novel prognostic maker for patients with gastric cancer that receive trastuzumab therapy." (PMID 35463314, 2022). "Pertuzumab is another targeted drug for gastric cancer based on ERBB2." (PMID 35069767, 2022).
gastric cancer (continued). "In our cluster analysis of the TCGA data of gastric cancer patients with N2 and N3 metastasis, the cases with high ERBB2 expression formed clusters with cases that showed high SMAD2 expression, but not with the cases with a high expression of TGFB1, which is an upstream cytokine of SMAD2 signaling." (PMID 35650563, 2022). "Notably, insulin receptor levels are visualised easily in three of the four gastric cancer cell lines and in the metastatic cells that represent the majority of gastric cancers that are triple-negative for ERBB2, FGFR2 or MET overexpression." (PMID 34554347, 2022). "It shows positive efficacy in patients with advanced gastric cancer with high expression of ERBB2." (PMID 35069767, 2022). "An identification of the proteins / genes related to HER2 / ERBB2 expression could contribute to new molecular target therapies for HER2-positive gastric cancer." (PMID 35650563, 2022). "ERBB2 c.1899-1G>A was previously reported in breast, lung, and gastric cancer." (PMID 36686783, 2022). "As a targeted drug for gastric cancer, trastuzumab could stop the formation of ERBB2 homologous dimers, prevent the activation of the signaling pathways of cell proliferation, and kill tumor cells through antibody-dependent cellular cytotoxicity." (PMID 35069767, 2022). "Accordingly, response could be documented for a gastric cancer PDO line with an ERBB2 amplification, as well as in an PDO with an ERBB2 pathway activating mutation." (PMID 33223522, 2021). "Furthermore, combination therapy with fluoropyrimidine-based drugs, platinum-based drugs and trastuzumab is used for human epidermal growth factor receptor 2 (HER2; also known as ERBB2)-positive metastatic gastric cancer." (PMID 34128042, 2021). "Cytoplasmic and/or nuclear staining is very rare (observed in gastric cancer) and is not considered for diagnostic determination of ErbB2 overexpression." (PMID 32591879, 2021). "In gastric cancer, 4%-7% of tumors were found to have ERBB2 amplification or HER2 overexpression." (PMID 34485109, 2021). "We next examined gastric cancer-derived ERBB2 amplified OE19 cells that are sensitive to lapatinib and found that a combination of lapatinib plus prednisone is more effective than lapatinib alone in a xenograft model and also detect a suppression of bypass RTK signaling by prednisolone." (PMID 34853306, 2021). "ErbB-2/HER2 has a high expression in gastric cancer, so it is used as a therapeutic target." (PMID 34095130, 2021). "Also, according to the KG, both calcium and rap1 signalling pathways have other gene/protein associations such as ERBB2, KRAS and CDH1, which are further associated with the gastric cancer disease." (PMID 34181736, 2021). "ERBB2 is widely expressed in epithelial populations of both normal samples (Normal_2, Normal_3, Normal_5, Normal_6, Normal_10, 5/10) and gastric cancer samples (Cancer_1, Cancer_2, Cancer_3, Cancer_4, Cancer_6, Cancer_7, Cancer_8, Cancer_9, and Cancer_10, 9/10) at high levels." (PMID 34975912, 2021). "Notably, ERBB2 is a synonym of Her2, which is targeted as an antibody (Trastuzumab) that has been approved for treatment against gastric cancer." (PMID 32089736, 2020). "In addition, PA inhibited HER2(ERBB-2) signaling cascade, which is involved in cell cycle progression, in gastric cancer cells." (PMID 33182770, 2020). "Septins stabilize ErbB2, an important oncoprotein, in gastric cancer cells." (PMID 31857849, 2019). "Finally, the expression of four hub genes (ERBB2, VIM, EGR1, and PSMB8) was found to be related to the prognosis of HER2-positive (HER2+) gastric cancer." (PMID 31949544, 2019). "Therefore, we concluded that GPAA1 promotes the interaction between EGFR and ERBB2 and the signalling of the downstream promoter of proliferation—Akt—to enhance the uncontrolled growth of gastric cancer cells." (PMID 31118109, 2019).
gastric cancer (continued). "While it is well-appreciated that ERBB2 (HER2) gene amplification and protein expression is a bona fide therapeutic target in the treatment of patients with breast and gastric cancers, more recent trials have drawn attention to its actionability in other cancer types." (PMID 31019892, 2019). "In addition, a satisfactory response rate has also been found with Lapatinib treatment for ERBB2-positive progressive gastric cancer." (PMID 30842786, 2019). "Indeed, experiments of antigen blocking by anti sLea antibody in a gastric cancer cell line result in a dramatic downregulation of the ERBB2 protein." (PMID 29462882, 2018). "Previously, we reported that ganetespib has anti-cancer effects on ErbB2+ gastric cancer cells." (PMID 29717218, 2018). "Additionally, ERBB2 amplification contributes to the maintenance of stem cell (GCSC) subpopulations of gastric cancer; the expression status of ERBB2 is related to disease progression and poor prognosis." (PMID 28284008, 2018). "Taken together, our findings first suggest that miR-1296-5p might be involved in the regulation on the migration and invasion of human gastric cancer cells at least in part via targeting ERBB2/Rac1 signaling pathway." (PMID 28099468, 2017). "Moreover, we examined the role of ERBB2 and Rac1 signaling on the migration and invasion of gastric cancer cells." (PMID 28099468, 2017). "Moreover, miR-1296-5p is obviously down-regulated in ERBB2-positive gastric cancer samples compared to ERBB2-negative gastric cancer samples." (PMID 28099468, 2017). "Mounting evidence proves that ERBB2 over-expression in gastric cancer leads to poor prognosis." (PMID 28160563, 2017). "Despite ErbB2 extracellular domain being a well-known target for glycosylation, its glycosylation profile and the molecular mechanisms through which it actively tunes tumorigenesis in gastric cancer (GC) cells remain elusive." (PMID 29143776, 2017). "This experiment demonstrated for the first time that the level of miR-3622b-5p was inversely correlated with the level of ERBB2 expression in human ERBB2-positive tumors, and that miR-3622b-5p induced the apoptosis of breast and gastric cancer cells by repressing ERBB2 expression." (PMID 28160563, 2017). "Interestingly, in ERBB2-positive gastric cancers, the miR-1296-5p expression was suppressed in a majority of metastatic lymph node tissues compared to non-metastatic gastric cancer samples." (PMID 28099468, 2017). "With regard to gastric cancer treatment, with the exception of trastuzumab (therapy based on the overexpression of HER2 protein and/or the amplification of its gene ERBB2), chemotherapy of localized and advanced gastric cancer still does not consider genotypic tumor characteristics." (PMID 27366209, 2016). "Despite these efforts, only a few genetic changes, including the amplification and/or overexpression of MET and ERBB2, as well as the mutations and downregulation of APC and RUNX3, have been associated with gastric cancer and the underlying molecular mechanisms remain largely undefined." (PMID 26942872, 2016). "Likewise, there were frequent CNGs of EGFR in a TCGA glioblastoma multiforme cohort (~45%), and of ERBB2 in nearly 14% of cases from a TCGA stomach cancer cohort." (PMID 27029057, 2016). "To this end we chose to examine the efficacy of the A5/F4 oligoclonal alone and in combination with trastuzumab using the NCI-N87 ERBB2+ gastric cancer xenograft model, as inhibiting ERBB3 in the setting of ERBB2+ gastric cancer represents a promising approach for the treatment of this disease." (PMID 25386657, 2014). "In addition, miR-375 overexpression suppressed the proliferation of human gastric cancer cells in vitro and the suppression effect was restored by ERBB2 overexpression." (PMID 24926380, 2014).